TNF (tumor necrosis factor)
Diseases named in the same sentence as TNF in open-access papers (continued):
Sharing a sentence is not in itself a finding about the gene and the disease.
esophageal cancer (continued). "Firstly, we found that pretreating cells with CPT prior to TNFα (an activator of NF-κB) stimulation significantly inhibited protein level of p65 NF-κB in the nuclear fraction of esophageal cancer cells, suggesting that CPT inhibited the activation of NF-κB pathway." (PMID 33898327, 2021). "Moreover, it was shown that due to increasing miR-155 expression by TAMs from esophageal cancer, the expression of IL-12, TNF-α, and Nos2 are enhanced, and tumor cells survive and migrate less in this condition." (PMID 34680504, 2021). "Besides these target genes, it has been recently reported that TNF is one of the target genes in esophageal cancer development." (PMID 23344184, 2012). "Additionally, probiotics possess anti-inflammatory properties as they can suppress chronic inflammation, a key factor in the development of esophageal cancer, by reducing the production of pro-inflammatory cytokines such as IL-6 and TNF-a, thus slowing or preventing cancer progression." (PMID 39346897, 2024). "Therefore, the purpose of this work was to address the question of whether inhibition of LDHA activity may affect the pro-migratory effects of TNF-α in esophageal cancers, with particular attention to the role of MMP9." (PMID 36555705, 2022). "The upregulation of SOD2 by TNF-α was inhibited by blocking the NF-κB pathway, suggesting that SOD2 via the NF-κB signaling pathway contributes to the proliferation of esophageal cancer cells." (PMID 36672191, 2023). "We revealed for the first time that LDHA inhibition blocks TNF-α-induced migration of esophageal cancer cells and effectively inhibits MMP9 expression in cells stimulated with TNF-α by attenuating activation of the ERK1/2-related signaling pathway." (PMID 36555705, 2022). "For example, active crosstalk between TNF-α/mTOR/S6K1 and the Hh pathway has been observed in esophageal carcinoma." (PMID 29695137, 2018). "Furthermore, DEX infusion decreased the plasma TNF-α concentration and improved the occurrence of POCD in patients undergoing surgical resections of colon, gynecological, gastric, and esophageal cancer." (PMID 36765695, 2023). "Although overall, the effect of TNF-α on LD5-dependent metabolic activity in esophageal cancer cells does not appear to be of great significance, our results strongly suggest that the presence of this cytokine enhances the Warburg effect in tumors." (PMID 36555705, 2022). "Taken together, our data indicate that RIPK3 and autocrine production of TNFα contribute to cisplatin sensitivity by initiating necrosis when the apoptotic pathway is suppressed or absent in esophageal cancer cells." (PMID 24959694, 2014). "FN1, TNF, and IL-6 may be potential target genes regulated by APE1 in esophageal cancer." (PMID 40330011, 2025). "Cytokines secreted during inflammation, such as interleukin-1 (IL-1) and tumor necrosis factor-α (TNF-α), as well as reactive oxygen species (ROS), could activate cyclooxygenase 2 (COX-2), which contributed to the development, metastasis, and neo-angiogenesis of esophageal cancer." (PMID 33029095, 2020).
leptospirosis (32 papers, 2009 to 2025). A contagious bacterial infection caused by spirochetes of the genus Leptospira. "In studies of patients with multiple clinical manifestations with leptospirosis, the severity of the clinical picture has been associated with various serum cytokines levels, such as TNF-α, IL-10, and IL-6, but this conclusion remains controversial." (PMID 35203344, 2022). "The increase in plasma concentrations of TNF-α is associated with poor prognosis in patients with leptospirosis." (PMID 35919644, 2022). "By contrast, other studies showed that low IL-10/TNF-α ratio was associated with leptospirosis, severe disease and fatal outcomes." (PMID 32264832, 2020). "IL-4, IL-6, IL-8, IL-10, IL-17A, and TNF-α levels in severe leptospirosis compared to mild disease, and an association between high IL-6, IL-8, IL-10 and fatal outcome." (PMID 26824356, 2016). "Leptospirosis-susceptible hamsters showed strong expression of IL-1β, IL-6, TNF-α, and COX-2 in infected organs, whereas leptospirosis-resistant mice showed accelerated expression of the anti-inflammatory IL-10." (PMID 26824356, 2016). "Two of the cytokines, TNF-α and IL-6, are strongly associated with the severity of disease and the mortality of leptospirosis." (PMID 22870312, 2012). "As well, elevated plasma concentrations of TNF-α have been associated with lethal outcome amongst leptospirosis patients, In a hamster model, late expression of the anti-inflammatory cytokines IL-4, TGF-β and IL-10 have been shown." (PMID 19488407, 2009). "High IL-10/TNF-α ratio was associated with leptospirosis and fatal outcomes." (PMID 32264832, 2020). "Notably, we also found that a high ratio of IL-10 to TNF-α was associated with death from leptospirosis, driven predominantly by IL-10 levels." (PMID 24069500, 2013). "Fatal leptospirosis has been previously associated with both high and low levels of TNF-α." (PMID 24069500, 2013). "TNF-α, proinflammatory IL-6, chemokine IL-8, and anti-inflammatory IL-10 were known to play important roles in the pathogenesis of leptospirosis." (PMID 40861768, 2025). "In severe leptospirosis, TNF-α and IL-10 levels increase, with IL-10 significantly higher in fatal cases." (PMID 40732660, 2025). "It has been noted that there was a high IL10: TNF-α ratio in the control dogs experiencing acute leptospirosis, as was also reportedly found in human patients with fatal outcomes of acute leptospirosis." (PMID 40732660, 2025). "Cytokines, particularly TNF-α, IL-6, IL-1β and IL-10, have been found to be higher in severe and even fatal forms of human leptospirosis compared to milder infections." (PMID 40986630, 2025). "Leptospirosis induces direct bacterial invasion of hepatocytes and triggers an inflammatory response by releasing inflammatory cytokines such as TNF- and IL-6." (PMID 39940058, 2025). "TLR2 involvement during the pathogenesis response against leptospirosis was observed through the decrease of IL1β, TNFα, IL6, NFκB, and IL10 secretion/expression due to deficient/knocked down of the TLR2 receptors." (PMID 39729468, 2024). "In patients with severe leptospirosis, elevated levels of IL-6, IL-10, and TNF-α have been observed during a cytokine storm." (PMID 38398036, 2024). "Those suffering from severe leptospirosis exhibit indications of a ‘cytokine storm' characterised by elevated levels of IL-6, TNF-alpha and many other cytokines compared to those with milder symptoms." (PMID 39610672, 2024). "A previous systematic review showed elevated levels of cytokines (IL-1β, IL-2, IL-4, IL-6, IL-8, IL-10, TNFα) in severe human leptospirosis compared with mild leptospirosis." (PMID 39729468, 2024). "Aligned with our findings, narrative reviews discussed the renal dysfunction associated with leptospirosis that resulted in secretion/expression of Fibronectin, iNOS, CCL2/MCP-1, TNFα, NFκB, CCL2/MIP2, CXCL1/KC through TLR2." (PMID 39729468, 2024).
leptospirosis (continued). "In severe leptospirosis in humans, two scenarios have been reported; either high IL-10 and low TNF-α or low IL-10 and high TNF-α." (PMID 35584087, 2022). "Significantly higher concentrations of IL-1β, IL-2, IL-4, IL-6, IL-8, IL-10, IL-17A, and TNF-α were found in sera of leptospirosis patients." (PMID 35927283, 2022). "In conclusion, the results show that TNF-α and IL-10 significantly increased in severe leptospirosis and IL-10 is significantly higher in fatal cases." (PMID 35919644, 2022). "Several earlier studies have identified significant expression of IL-1β, IL-2, IL-4, IL-6, IL-8, IL-10 and TNF-α in severe leptospirosis." (PMID 35584087, 2022). "Our results suggest determining and balancing [delete] the level of TNF-α and IL-10 in patient’s serum as useful prognostic factors in leptospirosis patients." (PMID 35919644, 2022). "Our results showed that the levels of TNF-α and IL-10 significantly increased in severe leptospirosis." (PMID 35919644, 2022). "Especially, TNF-α and the interleukins IL-1β, IL-2, IL-4, IL-6, IL-8, and IL-10 were elevated in severe leptospirosis cases, whereas TNF-α, IL-6, IL-8, IL-10, interferon-γ, and soluble TNF receptor 1 were elevated in high fatality cases." (PMID 35237527, 2021). "IL-1b, IL-2, IL-4, IL-6, IL-8, IL-10 and TNF-α levels were found to be significantly higher in severe than in mild leptospirosis." (PMID 32264832, 2020). "Fatal outcomes from Plasmodium falciparum malaria showed elevated levels of IL-6, IL-10 and TNF-α than in survival which was comparable to the results on leptospirosis." (PMID 32264832, 2020). "IL-1β, IL-6 and TNF-α were proposed to be pro-inflammatory cytokines which enhance the inflammatory response in leptospirosis." (PMID 32264832, 2020). "Nevertheless, results among the complicated leptospirosis showed elevated levels of IL-6 and TNF-α which shows a higher degree of pro-inflammatory action." (PMID 32264832, 2020). "TNF-α is the most studied cytokine in leptospirosis and has been found to be a marker for clinical outcome." (PMID 31114579, 2019). "Elevation of serum IL-10 and IL-17A levels and significant elevation of serum IL-21 (p=0.002), IL-23 (p=0.002), and TNF-α (p=0.039) were observed among leptospirosis patients compared to the healthy control group." (PMID 30123395, 2018). "The mean concentrations of IL-21, IL-23, and TNF-α among the leptospirosis patients were 14.69 pg/ml ± 13.1, 54.06 pg/ml ± 28.1, and 700 pg/ml ± 619, respectively." (PMID 30123395, 2018). "Among the five cytokines tested, IL-21 (p=0.002), IL-23 (p=0.002), and TNF-α (p=0.003) were significantly elevated among leptospirosis patients compared to the healthy controls." (PMID 30123395, 2018). "Another important proinflammatory cytokine elevated in leptospirosis is TNF-α which is generated predominantly from activated macrophages and also from nonimmune cells." (PMID 30123395, 2018). "The serum cytokine levels of IL-10, IL-17A, IL-21, IL-23, and TNF-α were investigated in 57 patients with leptospirosis and 12 healthy controls using a commercially available ELISA kit (Mabtech, Sweden)." (PMID 30123395, 2018). "According to the present study, IL-21, IL-23, and TNF-α levels were significantly elevated among leptospirosis patients compared to the healthy controls." (PMID 30123395, 2018). "In summary, this study shows that dogs with naturally-occurring leptospirosis display a cytokine and enzyme pattern characterized by higher 5-LO and lower TNF-α expression than dogs with AKI from other origin." (PMID 26824356, 2016). "Leptospirosis cases with fatal outcomes exhibited higher IL-10 but lower TNF-α levels than survivors, and a positive correlation was identified between the IL-10/TNF-α ratio and fatal outcomes." (PMID 26146835, 2015). "Earlier reports showed that TNF-α, an important proinflammatory cytokine produced mainly by mononuclear macrophages, is elevated in sera from leptospirosis patients." (PMID 22870312, 2012).
leptospirosis (continued). "A high IL-10/TNFα ratio was reported as correlated with poor outcome in septic patients, contrary to the opposite results obtained in one limited study reported in leptospirosis." (PMID 20076757, 2010). "Dysfunctional regulation of the levels of the cytokines/chemokines IL-6, IL-8, IL-10, IFN-ɣ, KC/GRO, MCP-1, MIP-1a, MIP-2 and TNF-α, after infection of C3H/HeJ mice with virulent Leptospira, were correlated to the severity of leptospirosis observed in this animal model." (PMID 39312584, 2024). "Severe leptospirosis may trigger a cytokine storm, characterized by elevated serum levels of IL-6, IL-10, and TNF-alpha, indicating widespread dissemination of the pathogen." (PMID 38398036, 2024). "Our results suggested determining the level of TNF-α in patient’s serum maybe as a favorable prognostic factor in leptospirosis patients." (PMID 35919644, 2022). "In addition, studies also reported IL-1β, IL-12P70 and TNF-α, levels as low or undetectable in leptospirosis patients and healthy controls." (PMID 32264832, 2020). "However, the present review found IL-1β to be low among leptospirosis patients, IL-6 to be elevated and TNF-α to be equivocal." (PMID 32264832, 2020). "Moreover, IL-21, IL-23, and TNF-α levels were significantly increased among leptospirosis patients with liver insufficiency." (PMID 30123395, 2018). "In addition, the level of serum TNF-α was higher in leptospirosis patients with pulmonary hemorrhage, and serum IL-6 level was associated with fatalities from severe pulmonary hemorrhage syndrome." (PMID 26146835, 2015). "The high expression level of TNF-alpha in HBMs may be related to the severe pathological symptoms of human leptospirosis." (PMID 24130911, 2013). "The cytokine profile revealed that the levels of at least sixteen cytokines were significantly elevated in the leptospirosis patients’ sera, including the major proinflammatory factors IL-1β, IL-6 and TNF-α, and the major anti-inflammatory factors IL-4, IL-10 and IL-13." (PMID 22870312, 2012). "Increased TNF production is a predictor of poor clinical outcome in patients with leptospirosis." (PMID 23132959, 2012). "An other study reported increased TNF-α levels in four out of eighteen leptospirosis patients." (PMID 19488407, 2009). "The levels of TNF-α were higher in CD4+T cells obtained from patients with severe and life-threatening manifestations of leptospirosis than in those from asymptomatic and heathy control subjects." (PMID 33789603, 2021). "Similar to the present review, IL-6, IL-8, IL-10, IP-10, MCP-1, TNF-α and VEGF were found to be elevated in DHF, a condition common to almost all endemic settings for leptospirosis." (PMID 32264832, 2020). "Although, the review produced valuable data on the possible role of cytokines in leptospirosis disease severity, there were equivocal findings with regards to IL-1β, TNF-α and IL-10/TNF- α ratio among the selected studies." (PMID 32264832, 2020). "Dogs with leptospirosis were characterized by a high 5-LO and low TNF-α expression compared to other dogs with AKI, although the decreased TNF-α expression was also seen in dogs with CKD." (PMID 26824356, 2016). "Notably, although TNF and IL-6 cytokines were increased after antibiotic treatment of patients with leptospirosis, no secretion of IL-1ß was found in this study." (PMID 40986630, 2025). "Interestingly, TNFα was also reported to have a similar prognosis value in leptospirosis, though these results were not confirmed in other studies." (PMID 20076757, 2010). "Notably, we observed the secretion/mRNA expression of several cytokines (IL6, IL8, IL-1β, TNFα, IFNγ, IL10, CCL2/MCP-1, CCL10, COX2, CXCL1/KC, CXCL2/MIP2) and immune effectors (hBD2, iNOS, Fibronectin, Oxygen, and Nitrogen reactive species) as key aspects of host TLR2 responses during leptospirosis." (PMID 39729468, 2024).
leptospirosis (continued). "For this, we evaluated the mRNA expression of a panel of immune related cytokines (IL-1α, IL-1β, IL-8, IL-10, TNF-α, TGF-β) and enzymes (5-LO, iNOS) in blood leukocytes from dogs with AKI and leptospirosis, including dogs with and without LAPH." (PMID 26824356, 2016).
leukopenia (32 papers, 2009 to 2026). "TfRMAb-based fusion proteins are associated with acute TfRMAb-mediated reticulocyte suppression, and TNF-α inhibitors including etanercept are potent immune modulators that can cause leukopenia and increase the risk of infections." (PMID 34972522, 2021). "Interestingly, long-term high-fat diet treatment caused leukopenia and TNF-α increase in mice." (PMID 35011585, 2021). "To control for the potential impact of leukopenia on TNF production, we normalized TNF levels to monocyte counts calculated using daily complete blood count with automated differential cell count analysis." (PMID 40433392, 2025). "Laboratory differences include a higher frequency of leukopenia, hypocomplementemia, and anti-dsDNA antibody positivity in anti-TNFα inhibitor-induced DIL, whereas classical DIL has a higher frequency of anti-histone antibody positivity." (PMID 39618753, 2024). "Severity of CLP in cGAS-/- mice was less severe than in wildtype (WT) mice, as indicated by mortality, serum LPS, cfDNA, leukopenia, cytokines (TNF-α, IL-6 and IL-10), organ histology (lung, liver and kidney) and spleen apoptosis." (PMID 34768881, 2021). "LPS as such induced a dramatic rise in TNF-alpha (p < 0.001), hyperthermia (p < 0.01), and severe leukopenia (p < 0.001)." (PMID 26703732, 2015). "In animals, the administration of ENT blockers attenuates LPS-induced leukopenia and tumor necrosis factor-α (TNF-α) production and reduces the severity of tissue injury in several inflammatory models." (PMID 22129171, 2011). "Another contributing factor may be the severe leukopenia caused by the virus, with a significant decrease in the number of CD4 and CD8 lymphocytes and elevation of interleukins (IL-2R, IL-6, IL-10, TNF-alpha) and other inflammatory markers." (PMID 35205852, 2022). "The expression of tumor necrosis factor (TNF)-α may contribute to the leukopenia in pigs infected with CSFV by promoting apoptosis." (PMID 29018607, 2017).